BMI1 (BMI1 proto-oncogene, polycomb ring finger)
Diseases named in the same sentence as BMI1 in open-access papers (continued):
Sharing a sentence is not in itself a finding about the gene and the disease.
pituitary tumor (7 papers, 2012 to 2024). A benign or malignant neoplasm affecting the pituitary gland. "Earlier reports describing pituitary tumors because of Rb loss described a similar localization and histology, and we tested whether Bmi1 overexpression has an enhanced role on top of Rb loss (GCre;RbLox/Lox;Bmi1LSL n = 12, GCre;RbLox/Lox n = 20)." (PMID 22574128, 2012). "We show here that Glial fibrillary acidic protein-Cre (GFAP-Cre) mediated conditional over expression of Bmi1 generates anterior and intermediate lobe pituitary tumors." (PMID 22574128, 2012). "By using a transgenic over expression model, we show that GFAP-Cre mediated transgenic over expression of Bmi1 is sufficient to drive the formation of pituitary tumors, a type of tumor that represents 10 to 25% of all intracranial neoplasms in humans." (PMID 22574128, 2012). "In conclusion, we show here that Bmi1 transgene over expression is sufficient to drive pituitary tumors and we also show that more than 50% of clinical pituitary adenomas have high expression of Bmi1." (PMID 22574128, 2012). "Deregulation of BMI1 has been revealed to affect apoptosis; thus, miR-128, which was downregulated in GH-secreting pituitary tumors, could also affect apoptosis by directly regulating BMI1." (PMID 25548562, 2014). "Moreover, miR-128 regulated PTEN expression and Akt activity in the pituitary tumor cells by interfering with the binding of BMI1 to PTEN promoter." (PMID 25548562, 2014). "Since deregulation of PTEN and BMI1 correlates with the invasive and metastatic phenotype of several human cancer types, it is possible that miR-26b and miR-128 regulate invasiveness of pituitary tumor cells by directly targeting PTEN and BMI1, respectively." (PMID 25548562, 2014). "Up regulation of miRNA-128 not only suppressed the colony formation ability and invasiveness of pituitary tumor cells but also suppressed pituitary GH3 tumor growth in xenografts via, Bmi-1." (PMID 24555688, 2014). "MiRNA-128 found to regulate its direct target Bmi-1 and PTEN-AKT pathway in pituitary tumors." (PMID 24555688, 2014).
gastric tumor (6 papers, 2010 to 2019). "In addition, we performed in situ hybridization of miR-15a in gastric tumor tissues and the results are consistent with qRT-PCR analysis that elevated miR-15a staining is associated with reduced expression level of Bmi-1 by IHC." (PMID 26894855, 2016). "Another possibility is that high levels of Bmi-1 are crucial in blocking MET process of advance stage gastric tumor in vivo." (PMID 26894855, 2016). "As a result, gastric tumor cells that have low levels of Bmi-1 will be slowly proliferating and insensitive to chemotherapy which target rapid proliferative cells." (PMID 26894855, 2016). "We have also studied the expression of Mel-18 and Bmi-1 in gastric tumors by immunohistochemistry (IHC)." (PMID 21059209, 2010). "QRT-PCR analysis showed that 35 of 71 (49.3%) fresh gastric tumor tissues overexpressed Bmi-1, and 46 of 71 (64.79%) expressed low levels of Mel-18, compared with paired normal gastric mucosal tissues." (PMID 21059209, 2010). "In a recent study, BMI1 overexpression was closely related with the Lauren's and Borrmann's classification and clinical stage in gastric tumors." (PMID 20170541, 2010). "To explore the therapeutic value of Huaier n-butanol extract in GC patients, we determined whether Bmi1 expression was increased in gastric tumours." (PMID 30679589, 2019). "The expression of Bmi-1 was quantified by IHC from 21 gastric tumor tissues." (PMID 26894855, 2016). "To probe this hypothesis, we studied the expression of Mel-18 and Bmi-1 in gastric tumors by QRT-PCR." (PMID 21059209, 2010). "IHC analysis of paraffin-embedded archival gastric tumor samples showed that 51 of 75 (83.6%) samples exhibited positive staining for BMI1 while only one sample out of 21 normal gastric mucosal tissue samples (1/21, 4.8%) was scored positive for BMI1." (PMID 20170541, 2010). "Next, we studied the expression of Mel-18 and BMI1 in gastric tumors by IHC." (PMID 20170541, 2010). "In addition, the expression of Bmi-1 and Mel-18 mRNA inversely correlates in gastric tumors." (PMID 21059209, 2010). "We quantified the expression levels of several miRNAs that were previously reported to suppress Bmi-1 protein expression in other tumor types using 25 gastric tumor specimens and the corresponding non-neoplastic gastric mucosa using qRT-PCR analysis." (PMID 26894855, 2016). "We found that most gastric tumor tissues (64.79%) expressed decreased mRNA levels of Mel-18, and there was a strong negative correlation between Bmi-1 and Mel-18 expression at mRNA level." (PMID 21059209, 2010).
intestinal tumor (6 papers, 2017 to 2025). "Since the discovery of specific ISC populations, including Lgr5+, Bmi1+, or Lrig1+ ISCs, and their ability to serve as the origin of intestinal tumor development, much interest has been focused on their function in the context of diet and aging." (PMID 29904634, 2018). "The results of this study show that all types of intestinal tumors contain Bmi1- or Lgr5-positive cells, which clonally expand to contribute to tumor propagation." (PMID 28176811, 2017). "The differences between the two types of Dll4 mutants in the expression of Lgr5 and Bmi1 markers in the small and large intestinal tumors were statistically significant." (PMID 28086833, 2017). "Therefore, given the observed reduction in the ApcMin/+ small and large intestinal tumor number in the Dll4 knock-out mice compared with the controls, we decided to analyse if Dll4 reduction was affecting the Lgr5+ and/or Bmi1+ stem cell expression in the tumors." (PMID 28086833, 2017). "This relationship between BMI1 and β-catenin helps to support our findings that BMI1 and nuclear β-catenin are colocalized and more highly expressed in high-LET-induced intestinal tumors." (PMID 37686516, 2023). "In support of this, it is noteworthy that BMI1+ cells appear independent of the Wnt pathway for their proliferation in contrast to LGR5+ cells, while BMI1+ and LGR5+ cells have been shown to represent distinct populations of cancer stem cells in intestinal neoplasms." (PMID 37048132, 2023). "In addition, as we only analysed the Lgr5 and Bmi1 positive stem cell populations, it is not certain if this pathway can affect similarly all the stem cells present in the intestinal tumors." (PMID 28086833, 2017).
mantle cell lymphoma (6 papers, 2012 to 2021). Mantle cell lymphoma is a rare form of malignant non-Hodgkin lymphoma affecting B lymphocytes in the lymph nodes in a region called the ``mantle zone''. "Moreover, BMI-1 was shown to mediate the survival of memory CD4 T cells as well as mantle cell lymphoma cells via direct binding to the NOXA gene locus and repression of NOXA mRNA expression through histone modifications." (PMID 26935956, 2016). "In recurrent mantle cell lymphoma (MCL SP) cells and cell lines, the low expression of miR-16 and the high expression of BMI1 could promote tumorigenesis and development by inhibiting apoptosis." (PMID 32999755, 2020).
ovarian tumor (6 papers, 2010 to 2025). "Effects of VEGFA and Bmi1 on ovarian tumor‐initiating cell abundance were further investigated in vivo." (PMID 28179359, 2017). "The enhanced efficacy observed here thus suggests that in addition to BMI1, the other targets of miR-15a and miR-16 are pathologically relevant and support ovarian tumor growth." (PMID 26918603, 2016). "It has been found that BMI1 is highly expressed in cervical, breast and ovarian tumor tissue compared to normal tissue." (PMID 25999024, 2015). "In our ovarian tumor specimens, a significant increasing expression of Bmi-1 was observed from benign cystadenoma to borderline tumor, and to carcinoma." (PMID 20377880, 2010). "Furthermore, histopathological and western blot analyses revealed that BMI-1 expression was higher in ovarian tumor tissues than in normal tissues." (PMID 41345229, 2025). "Similarly, the expression of BMI-1 was markedly increased in spheroids derived from primary OC cells freshly isolated from human ovarian tumors and subsequently decreased following DHA treatment." (PMID 41345229, 2025). "BMI-1 has been identified in experimental studies of OC (cell lines, clone derivation, and animal experiments), both in protein and the protein-coding gene, and in human ovarian tumors or ascites fluid samples." (PMID 34199929, 2021). "BMI1 knockdown abolished VEGFA‐dependent increases in sphere formation and in ovarian tumor‐initiating cells in vivo." (PMID 28179359, 2017).
astrocytomas (5 papers, 2009 to 2015). "Significant differences were observed in the relative expression of Bmi-1 and CCND1 between grades II and IV astrocytomas (p<0.001 for both), with a 1.15-fold and 1.31-fold increase in their expression in GBM samples, respectively." (PMID 26317630, 2015). "Our gene expression results corroborate these findings, showing that Bmi-1 was overexpressed in all tumor grades evaluated; this expression was 1.15-fold higher in GBM compared with that in grade II astrocytomas." (PMID 26317630, 2015). "In grade II astrocytomas, a moderate inverse correlation was observed only between the expression of RB1 and Bmi-1 (r = -0.5968, p = 0.001)." (PMID 26317630, 2015).
biliary tract cancer (5 papers, 2016 to 2025). "To verify these statements, we used PTC-209 (BMI1 Polycomb Ring Finger Oncogene (BMI1) inhibitor) that we recently demonstrated to inhibit clonogenic growth in biliary tract cancer cells." (PMID 29510509, 2018). "BMI1 is a core component of the polycomb repressive complex 1 (PRC1) and is up-regulated in biliary tract cancer (BTC), contributing to aggressive clinical features." (PMID 26623561, 2016). "This is in agreement with the recent finding showing that PTC-209 did not affect BMI-1 transcript levels but downregulated BMI-1 protein levels in biliary tract cancer cells." (PMID 29262596, 2017). "Further studies showed that PTC-209 downregulated the level of Bmi-1 protein without affecting the levels of Bmi-1 transcript in MM cells and biliary tract cancer (BTC) cells, suggesting that it might also regulate Bmi-1 expression at the posttranscriptional level." (PMID 31695609, 2019).
malignant glioma (5 papers, 2013 to 2023). A grade III or grade IV glioma arising from the central nervous system. "In this study, we demonstrate for the first time that Bmi-1 also promotes tumor angiogenesis in malignant gliomas." (PMID 23383216, 2013). "In vivo RNAi screening for BMI1 targets suggests that the TGF-β/BMP-ER stress pathways are key regulators of neural- and malignant glioma-stem cell homeostasis." (PMID 27304053, 2016).
metastatic disease (5 papers, 2016 to 2022). "Recently, genetic inhibition of BMI1 was found to eliminate BMI1-expressing CSCs, resulting in the prevention of metastatic tumor growth and relapse in HNSCC." (PMID 35629138, 2022).
osteoporosis (5 papers, 2014 to 2024). A condition of reduced bone mass, with decreased cortical thickness and a decrease in the number and size of the trabeculae of cancellous bone (but normal chemical composition), resulting in increased fracture incidence. "Our results demonstrate that administration of PTH1-34, a drug currently used for treating osteoporosis, partially rescues haematopoietic defects in Bmi1-deficient mice by improving the bone marrow microenvironment." (PMID 24705625, 2014). "In previous studies we demonstrated that Bmi1 deficiency results in premature osteoporosis with reduced osteoblast formation and osteogenesis 10, whereas overexpression of Bmi1 in MSCs elicited antiosteoporosis effects by enhancing osteoblast formation and osteogenesis." (PMID 35173529, 2022). "In the present study, we asked whether the improvement in premature aging and osteoporosis caused by Bmi1 lymphocyte overexpression in PthrpKI/KI mice was associated with inhibition of oxidative stress." (PMID 27373231, 2016). "Importantly, we found that PTH1-34 administration partially reversed premature osteoporosis occurred in Bmi1-deficient mice." (PMID 24705625, 2014). "In PTHrP1–84 knockin (PthrpKI/KI) mice, the expression levels of Bmi1 are reduced and potentially can mediate the premature osteoporosis observed." (PMID 27373231, 2016). "To determine whether Bmi1 overexpression in lymphocytes could improve the premature osteoporosis of PthrpKI/KI mice, we examined the effect of Bmi1 overexpression in lymphocytes on bone volume and osteoblastic indices in PthrpKI/KI mice." (PMID 27373231, 2016). "We therefore asked whether Bmi1 overexpression in lymphocytes could improve the growth arrest and premature osteoporosis in PthrpKI/KI mice." (PMID 27373231, 2016). "The mice were treated with PTH1-34 (containing the first 34 residues of mature PTH), an anabolic drug currently used for treating osteoporosis, and compared with the vehicle-treated Bmi1-/- and wild-type littermates in terms of skeletal and haematopoietic phenotypes." (PMID 24705625, 2014). "The results indicate the administration improves the microenvironment and rescues haematopoietic defects in Bmi1-null mice, thereby revealing a potential value of PTH1-34, an anabolic drug for osteoporosis, for repairing haematopoietic defects." (PMID 24705625, 2014).
pancreatitis (5 papers, 2013 to 2023). Inflammation of the pancreas. "The gene is required for regeneration (e.g., after pancreatitis), and inhibition of BMI1 has been shown to upregulate the production of reactive oxygen species, which is an essential step for the onset of pancreatic carcinogenesis." (PMID 36982172, 2023). "Thus, the expression of the histone modifying PRC1 components Bmi1 and Ring1b and the level of the histone modification H2AK119ub were analyzed at two different points in time following cerulein-induced pancreatitis." (PMID 26716510, 2016). "Pancreatic tumorspheres also demonstrated high levels of Bmi1." (PMID 23437065, 2013). "Bmi1 expressing acinar and islet cells have been found in the murine pancreas and Bmi1 plays a key role in the recovery of the acinar compartment after cerulein-induced pancreatitis and diphtheria toxin-mediated acinar cell ablation in mice." (PMID 23437065, 2013).
prostate tumor (5 papers, 2013 to 2025). "BMI1 protein is (i) secreted by CaP cells, (ii) increased in the apical region of epithelial cells and stromal region in prostatic tumors, and (iii) detected in human blood." (PMID 23308129, 2013). "The success of docetaxel therapy against prostatic tumors in a xenograft mouse model was observed to be highly dependent on the level of BMI1." (PMID 23671559, 2013). "We show that targeting BMI1 improves the outcome of docetaxel therapy in animal models bearing chemoresistant prostatic tumors." (PMID 23671559, 2013).
renal cell carcinoma (5 papers, 2015 to 2018). "Functional studies on miR-708 in renal cell carcinoma (RCC) showed that miR-708 was identified as target for survivin, Zinc finger E-box-binding homeobox 2 (ZEB2) and B lymphoma Mo-MLV insertion region 1 homolog (BMI1), and expression level of miR-708 was widely reduced in RCC patients." (PMID 30463333, 2018).
sarcoma (5 papers, 2011 to 2024). A usually aggressive malignant neoplasm of the soft tissue or bone. "We first examined Oncomine and determined the expression of BMI1 in both adult and pediatric sarcomas." (PMID 33523558, 2021). "It is intriguing to posit a broad role for BMI1 involvement in the Hippo pathway across sarcomas and to speculate that BMI1 inhibition may provide a method of activating the Hippo pathway in these malignancies." (PMID 33523558, 2021). "Finally, while our studies focused on ARMS, we find that BMI1 is broadly expressed in multiple pediatric and adult sarcomas, raising the possibility that BMI1 may shape the initiation, maintenance, and progression of diverse sarcoma histotypes." (PMID 33523558, 2021). "They provide a strong foundation for investigating the utility of BMI1 inhibition in ARMS and should spur further investigations of BMI1 and other PRC1/2 proteins as potential dependencies in RMS and other sarcomas." (PMID 33523558, 2021). "Collectively, these findings provide an initial framework for targeting BMI1 in ARMS and additional sarcomas." (PMID 33523558, 2021). "To investigate BMI1 as a potential therapeutic vulnerability in ARMS, we sought to define its expression pattern in sarcomas, broadly considered." (PMID 33523558, 2021).
tongue squamous cell carcinoma (5 papers, 2010 to 2024). A squamous cell carcinoma that arises from the tongue. "In conclusion, loss of Bmi-1 immunoexpression seems to correlate with clinical outcome of oral tongue SCC, in contrast to Snail or c-myc immunoexpression." (PMID 20145620, 2010). "It has been demonstrated that BMI1 functionally marks keratinocytes with cancer stem cell properties in tongue SCCs, and promotes chemotherapy and immunotherapy resistance." (PMID 38951654, 2024).
colitis (4 papers, 2015 to 2025). Inflammation of the colon. "The expression level of cycling stem cell marker Lgr5 was decreased more than 50%, and the expression level of Bmi1 decreased about 20% in Dclk1f/f mice after DSS treatment, suggesting a decrease in both stem cell populations following DSS-induced colitis." (PMID 26285154, 2015).
colorectal tumors (4 papers, 2018 to 2022). "Here we report that the novel synthetic small molecule compound QW24 depletes BMI-1 at the protein level, significantly impacting the growth of CICs and reducing colorectal tumor growth and metastasis." (PMID 31640758, 2019). "Furthermore, the Cancer Genome Atlas (TCGA) database showed BMI-1 was significantly overexpressed in colorectal tumors compared with normal tissues in patients, and the cases with higher expression levels of BMI-1 showed worse survival rates than cases with lower expression levels." (PMID 31640758, 2019). "Moreover, tumors formed in c-PTIO-treated animals showed a downregulation of β-catenin and Bmi1 expression, which is a key protein required for CSC function in colorectal tumors and represents an effective target for controlling tumor growth." (PMID 29329541, 2018).